HROB (homologous recombination factor with OB-fold)
Description:
DNA-binding protein involved in homologous recombination that acts by recruiting the MCM8-MCM9 helicase complex to sites of DNA damage to promote DNA repair synthesis. A C-terminal region including the OB-fold stimulates the helicase activity of MCM8-MCM9 probably by altering its conformation.
Synonyms: C17orf53; MGC3130; MCM8IP; ODG11
Tractability: PROTAC: ubiquitination databases record sites on it.
Gene: Protein-coding gene on chromosome 17 (44,141,903 to 44,162,481, forward strand). Ensembl gene ENSG00000125319.
Subcellular location: Nucleus; Chromosome
Subcellular location (Human Protein Atlas): Cytosol; Nucleoplasm
Gene Ontology:
Molecular function: protein binding; single-stranded DNA binding
Biological process: DNA damage response; DNA synthesis involved in DNA repair; interstrand cross-link repair; female gamete generation; male gamete generation; recombinational repair
Cellular component: chromosome; nucleus; site of DNA damage
Genetic constraint (gnomAD): Loss-of-function variants: 44 observed, 62.81 expected, observed/expected ratio (o/e) 0.7, 90% interval 0.55 to 0.9. The upper end of that interval is the gene's LOEUF score, 0.9, which puts it in group 3 of 6, group 1 being the genes least tolerant of losing a copy. Missense variants: 714 observed, 833.14 expected, observed/expected ratio (o/e) 0.86, 90% interval 0.81 to 0.91. Synonymous variants: 301 observed, 328.99 expected, observed/expected ratio (o/e) 0.91, 90% interval 0.83 to 1.01.
Homologues: Orthologues: chimpanzee HROB (96% identical), macaque HROB (92% identical), dog HROB (71% identical), pig HROB (71% identical), rabbit HROB (70% identical), rat Hrob (64% identical), mouse Hrob (64% identical), guinea pig Hrob (46% identical), tropical clawed frog HROB (33% identical), zebrafish hrob (33% identical).
Diseases named in the same sentence as HROB in open-access papers:
HROB is named in the same sentence as 10 diseases in open-access papers, as found by Europe PMC text mining. Sharing a sentence is not in itself a finding about the gene and the disease. The quoted sentences say what the papers report.
Infertility (2 papers, 2022 to 2024). "Previous studies found that HROB, previously known as uncharacterized C17ORF53, was highly conserved in vertebrates and disruption of HROB gene could induce infertility by depleting germ cells." (PMID 35903352, 2022).
Fanconi anemia (1 paper, 2021). Fanconi anemia (FA) is a hereditary DNA repair disorder characterized by progressive pancytopenia with bone marrow failure, variable congenital malformations and predisposition to develop hematological or solid tumors. "In LXF-289 cells, the NHEJ and Fanconi anemia pathways were strongly represented among the top hits enriched, as well as MCM8, MCM9, and HROB, genes that have previously been implicated in HR." (PMID 33788831, 2021).
lung adenocarcinoma (1 paper, 2026). A carcinoma that arises from the lung and is characterized by the presence of malignant glandular epithelial cells. "HROB, which is a DNA-binding protein linked to various cancers, has an unclear role in lung adenocarcinoma (LUAD)." (PMID 41526502, 2026).
cancer (5 papers, 2020 to 2026). A tumor composed of atypical neoplastic, often pleomorphic cells that invade other tissues. "Given the evidence from the present study and previous studies, HROB is likely a gene associated with DNA replication, which is essential for cancer progression." (PMID 35903352, 2022). "In accordance, we characterized HROB as a nuclear, chromatin-bound protein showing an S-phase-specific and proliferation-associated expression with downregulation in quiescent cells and upregulation in many different cancer entities." (PMID 39766854, 2024). "Consistent with a proliferation-dependent expression, database analyses revealed HROB to be upregulated in many different cancer entities compared to the corresponding healthy tissue." (PMID 39766854, 2024). "We also analyzed the association between HROB expression and cancer stemness and immune infiltration of cancer-associated fibroblasts (CAFs) and CD8+ T cells in pan-cancer." (PMID 35903352, 2022). "Here, we explored the potential relationship between HROB expression and cancer stemness of TCGA tumor tissues." (PMID 35903352, 2022). "Third, our results demonstrated that the HROB expression level was significantly correlated with the cancer stemness of primary tumor tissues in TCGA datasets." (PMID 35903352, 2022). "We also investigated the relationship between HROB expression and cancer stemness, immune cell infiltration of tumor tissues." (PMID 35903352, 2022). "In most cancer entities, a high HROB expression correlates with a poor prognosis." (PMID 39766854, 2024). "This study found that HROB could be a potential biomarker for multiple cancer types and may play an oncogenic role in tumorigenesis." (PMID 35903352, 2022). "HROB expression was robustly correlated with cancer stemness." (PMID 35903352, 2022). "Besides, several studies found that HROB may promote chemoresistance against various cancer therapeutic agents." (PMID 35903352, 2022). "Our results demonstrated that HROB may be a key molecule in promoting cancer stemness." (PMID 35903352, 2022). "However, although these results suggested that HROB promotes tumorigenesis in various tumor types, the evidence of these studies is relatively limited and the prevalence and predictive value of HROB in pan-cancer is unclear." (PMID 35903352, 2022).
tumor (3 papers, 2022 to 2026). "In summary, this study showed that HROB was overexpressed in various tumor types and associated with the advanced disease stage and poor patient prognosis." (PMID 35903352, 2022). "High HROB expression is associated with more aggressive tumour characteristics and poorer prognosis of LUAD, with a hazard ratio of 1.815 being observed (P = 0.004), thus suggesting that HROB could serve as an independent prognostic biomarker." (PMID 41526502, 2026). "Collectively, our results showed that high HROB expression might be a risk prognostic factor for various tumor patients." (PMID 35903352, 2022). "The pooling results of these datasets confirmed that HROB is overexpressed in various tumor types, though counterexamples have also been observed in several datasets." (PMID 35903352, 2022). "Meanwhile, we found that the HROB expression significantly decreased in kidney chromophobe (KICH) tumor tissues by comparing with the corresponding non-tumor tissues." (PMID 35903352, 2022). "To validate HROB differential expression between tumor and non-tumor tissues, we used Oncomine database to investigate the HROB expression pattern in other datasets." (PMID 35903352, 2022). "Previous studies have shown that HROB may play an oncogenic role by promoting cell proliferation and chemoresistance in several tumor types." (PMID 35903352, 2022). "Second, our results showed that higher HROB expression may be associated with poor prognosis (OS, DSS, and PFI) in patients with various tumor types." (PMID 35903352, 2022). "In addition, we also found that high HROB expression was significantly correlated with the advanced stage in several tumor types." (PMID 35903352, 2022). "These evidences suggested that HROB may play an oncogenic role by promoting cell proliferation and chemoresistance in various tumor types." (PMID 35903352, 2022). "These evidences suggested that HROB may be a potential prognostic biomarker for tumor patients." (PMID 35903352, 2022). "Similar analysis was used to investigate the relationship between HROB expression and PFI in TCGA tumor patients." (PMID 35903352, 2022). "First, we examined HROB expression in tumors and corresponding non-tumor tissues and found that HROB was significantly overexpressed in up to 17 tumor types." (PMID 35903352, 2022). "However, the evidences of these studies were relatively implicative and the oncogenic role of HROB has not been systemically established in any tumor types." (PMID 35903352, 2022).
HROB also shares sentences with these, for which no sentence is quoted: paraganglioma (1 paper); pheochromocytoma (1); prostate adenocarcinoma (1); testicular germ cell tumor (1); thymoma (1).